APOB (apolipoprotein B)
Diseases named in the same sentence as APOB in open-access papers (continued):
Sharing a sentence is not in itself a finding about the gene and the disease.
atherosclerosis (continued). "Apolipoprotein B (ApoB), a structural protein for LDL and very low-density lipoproteins, is implicated in atherosclerosis progression." (PMID 40070586, 2025). "While the precise antigen epitopes driving adaptive T-cell responses in atherosclerosis remain under investigation, growing evidence highlights native and oxidized ApoB-derived epitopes as critical contributors." (PMID 40552286, 2025). "These children showed elevated LDL cholesterol and apolipoprotein B levels, along with increased intima-media thickness - an early marker of atherosclerosis." (PMID 40677483, 2025). "ApoB is the core structural protein of atherogenic lipoproteins (such as Lp (a), LDL, VLDL), and atherosclerosis is the underlying cause of heart attacks." (PMID 40951435, 2025). "By reducing ApoB levels, the consumption of almonds interferes with the development of atherosclerosis by reducing the ferrying of cholesterol into arterial plaques." (PMID 40944180, 2025). "Similar changes as in atherosclerosis, such as accumulation of apolipoprotein B-100 and oxidatively and otherwise modified lipids, have been detected in degenerated and ruptured sIA walls." (PMID 40498464, 2025). "In literature, it has been reported that rats were resistant to atherosclerosis development since lipoproteins containing apoB such as (LDL, and VLDL) are of low level." (PMID 39266573, 2024). "Available data indicates that lipid-associated proteins, including PCSK9, are associated with increased atherosclerosis-associated lipid markers (total cholesterol, LDL-C, APOB), which is consistent with our MR analysis results on cardiovascular risk factors." (PMID 38689297, 2024). "Future research should explore additional lipid indicators, such as apolipoprotein A1 and apolipoprotein B, to gain a more comprehensive understanding of lipid metabolism in relation to frailty and atherosclerosis." (PMID 38781179, 2024). "ApoB, a pivotal element in addressing this issue, indicates the total number of atherosclerosis-inducing lipoprotein particles present in the bloodstream, thus displaying the atherosclerotic disease’s risk level." (PMID 38310324, 2024). "The expression levels of proteins associated with the lipid metabolism (LPA, APOB, and PCSK9) were associated with increased levels of atherosclerosis-promoting lipid indicators [Total Cholesterol, Low-density Lipoprotein (LDL)]." (PMID 38689297, 2024). "Other lipoproteins, such as lipoprotein(a) [Lp(a)] and apolipoprotein B (APO-B), have also been found to be associated with the risk of atherosclerosis." (PMID 38539180, 2024). "The major structural protein of TRLs, apolipoprotein B (ApoB), can flux across endothelium and be trapped in the artery wall, initiating atherosclerosis by releasing cholesterol to macrophages." (PMID 38413437, 2024). "In this line, elevated levels of apoB and LDL cholesterol are well-established risk factors for atherosclerosis and cardiovascular disease." (PMID 38978811, 2024). "Concurrently, several studies indicate that the ratio of ApoB/ApoA1 can reflect the cholesterol balance between atherosclerosis and anti-atherosclerotic lipoprotein particles, and can better predict cardiovascular risk." (PMID 38310324, 2024). "While apoA-I and apoB hold promise as biomarkers, potentially traditional lipoproteins in terms of enhanced accuracy and practicality in predicting arterial atherosclerosis in cardiovascular diseases." (PMID 38978811, 2024). "The retention of low-density lipoprotein cholesterol (LDL-c) and other cholesterol-rich, apolipoprotein B (ApoB)-containing lipoproteins contributes to the development of atherosclerosis." (PMID 39420941, 2024). "Apolipoprotein-B (APOB)-containing lipoproteins, including low-density lipoprotein (LDL), are the causal agents of atherosclerosis due to their ability to be retained, modified and engulfed at susceptible sites in the vasculature." (PMID 39196121, 2024).
atherosclerosis (continued). "Meanwhile, LDL and apolipoprotein B (apo B) play a central role in the initiation and progression of atherosclerosis." (PMID 38887452, 2024). "While many of the atherogenic properties of Lp(a) are mediated by apo(a), the apoB component not only provides structural integrity but also contributes to the promotion of atherosclerosis." (PMID 39456811, 2024). "ApoB molecules are carried by a variety of lipoproteins involved in the development of atherosclerosis, such as chymosin, LDL cholesterol and lipoprotein (a) particles." (PMID 38789961, 2024). "In the lipid and atherosclerosis pathway map, APOB in the core target is involved in early lipid droplet formation, and APOB gene expression is upregulated in ALD patients as shown in the GSE100901 database." (PMID 38905402, 2024). "Only a few studies have been conducted in children, but it has been shown that ApoB levels predict subclinical atherosclerosis in adulthood better than cholesterol levels." (PMID 38392258, 2024). "They found that the sensitivity of predicting MACE in the 3-month follow-up period with the ApoB/ApoA1 ratio was 84%, and the specificity of predicting the number of atherosclerosis vessels in the 1-year follow-up period was 81%." (PMID 38310324, 2024). "Studies have alsoshown that increased plasma levels of apolipoprotein B (apoB) and smalldense LDL are crucial determinants associated with atherosclerosis in T2DM." (PMID 39742220, 2024). "For the successful development of human atherosclerosis vaccines, foundational questions about immunity to ApoB/LDL-C and advancements in vaccine technology must be addressed." (PMID 39766344, 2024). "For instance, an ApoB p6 vaccine was protective in younger mice but worsened atherosclerosis in older, pre-fed mice." (PMID 39766344, 2024). "Familial hypercholesterolemia (FH), probably the most common monogenic dyslipidemia, is regulated by three primary genes (LDL-R, APOB, and PCSK9) and can cause premature atherosclerosis and cardiovascular complications." (PMID 37047642, 2023). "The ApoB/ApoA-I ratio indicates the balance between LDL-C and HDL-C, an imbalance of which accelerates the development of atherosclerosis and thereby increases the risk of ischemic stroke." (PMID 38274879, 2023). "Recently, mounting evidence showed that the quantity of apoB particles that entered and were retained within the arterial wall was the principal determinant of atherosclerosis." (PMID 37559117, 2023). "A critical driver of atherosclerosis, the apolipoprotein B gene, was upregulated in the arteries in carriers of haplogroup I1." (PMID 37510926, 2023). "An important component of these atherogenic lipoproteins is Apolipoprotein B (Apo B) that promotes the accumulation of LDL in the intima initiates atherosclerosis." (PMID 36984867, 2023). "The infiltration and retention of lipoprotein-containing Apolipoprotein B (ApoB) in the arterial wall is a key initiating event that initiates the inflammatory response and promotes the development of atherosclerosis." (PMID 38149053, 2023). "The Multi-Ethnic Study of Atherosclerosis showed that the ApoB/ApoA-I ratio better predicts coronary heart disease than standard lipid measurements." (PMID 38292957, 2023). "ApoB is a constituent of lipoproteins that contribute to the development of atherosclerosis, specifically LDL." (PMID 38292957, 2023). "ApoB is known to be a sensitive marker of atherosclerosis and its serum levels are increased early, before the appearance of any other lipid dysregulation." (PMID 38138907, 2023). "Several immunogenic epitopes have been identified and used as vaccine antigens against atherosclerosis in animal models derived from mouse ApoB (Apolipoprotein B)." (PMID 37373933, 2023). "After adjustment for other major CV risk factors, including HDL-C, fasting glucose, waist circumference, pulse pressure and pack-years of smoking, the impact of ApoB on subclinical atherosclerosis declined." (PMID 36975891, 2023).
atherosclerosis (continued). "Prior research has established the significant involvement of ApoB, specifically ApoB-100, in the advancement of atherosclerosis through its facilitation of atherogenic lipoprotein assembly." (PMID 38260151, 2023). "Many population studies on atherosclerosis have also identified elevation of low-density lipoprotein (LDL) cholesterol and apolipoprotein B (APOB) 100 to be associated with risk of atherosclerosis related cardiovascular events." (PMID 37762360, 2023). "The next most promising alternative therapy for the treatment of atherosclerosis is the direct reduction of ApoB levels." (PMID 38274879, 2023). "Currently, the reagent inhibits the production of ApoB and is mainly used for treating atherosclerosis." (PMID 37124758, 2023). "The most probable atherosclerosis-antigen is the low density lipoprotein (LDL) and its associated molecules, including its oxidized form, oxLDL, as well as its core protein, Apolipoprotein B." (PMID 37681883, 2023). "The ratio of low-density lipoprotein cholesterol (LDL-C) to apolipoprotein B (Apo B) is the valid indicator of atherosclerosis." (PMID 36949432, 2023). "A critical driver of atherosclerosis, the apolipoprotein B gene, was upregulated in arteries from carriers of haplogroup I1." (PMID 37510926, 2023). "ApoB/ApoA1 is a balance index reflecting antiatherosclerotic lipoprotein and promoting atherosclerosis in the plasma." (PMID 37063111, 2023). "At present, lipid-lowering therapy by reducing the production of ApoB is mainly used in patients with atherosclerosis." (PMID 37124758, 2023). "Following the 16-week trial, mice in the resolution of the atherosclerosis group (res) were injected with anti-sense oligonucleotide (ASO) to apolipoprotein B (ApoB) and were fed a normal chow diet." (PMID 37681883, 2023). "As measurement methods for apoB have become more and more accessible, research interest in this molecule has considerably increased, and so has its potential as an atherosclerosis biomarker." (PMID 37629496, 2023). "The lipoprotein (a) [Lp(a)] combining an apolipoprotein(a) [apo(a)] with an apolipoprotein B 100 (apoB100) of LDL was also a predictor for atherosclerosis and CVD." (PMID 35578238, 2022). "The three essential elements involved in the pathogenesis of atherosclerosis are apoB, endothelial permeability, and binding of lipoproteins in the intima." (PMID 36439997, 2022). "Atherosclerosis begins to form as apolipoprotein B lipoproteins accumulate within vessel walls beneath the endothelial lining." (PMID 36017084, 2022). "ScRNA-seq revealed that expanded plaque T cells consistently exhibited a mixed TH1/TH17 phenotype during atherosclerosis, whereas ApoB+ T cells formed several clusters with mixed TH signalling." (PMID 36267275, 2022). "Mucosal administration of apoB peptides, as well as subcutaneous injection of apoB peptides with or without aluminum-based adjuvants, have all been shown to inhibit atherosclerosis in experimental models through the activation of Tregs." (PMID 35269559, 2022). "It is also proposed that clinicians should consider the apoB lipoprotein lowering strategy to complement existing clinical practice for atherosclerosis treatment." (PMID 35371605, 2022). "In cardiovascular disease, for example, apolipoprotein B levels have become a key player in atherosclerosis." (PMID 36568987, 2022). "The APOB gene mutations cause Familial Defective Apolipoprotein B-100 (FDB), an autosomal dominant disease associated with an increased risk of atherosclerosis and CAD." (PMID 35743896, 2022). "This lipid retention occurs primarily in the deep intima based on the charge-charge interaction between apoB and biglycan and decorin secreted in high amounts by SMCs in this region, and prior to any significant monocyte infiltration in human atherosclerosis." (PMID 35795646, 2022).
atherosclerosis (continued). "Atherosclerosis is initiated by the oxidation and glycosylation of the apolipoprotein B (Apo-B) contained in low density lipoprotein (LDL) particles, which transport cholesterol and triglycerides to tissues." (PMID 35321702, 2022). "The genes that were differentially expressed in the lipid and atherosclerosis pathway were APOB (P = 0.008), CD36 (P = 0.040), CALM1, CALM2, CALM3 (P = 0.015), and HSPA8 (P = 0.047)." (PMID 36506940, 2022). "Active immunization with the apolipoprotein B-100 (ApoB-100) peptide P210 reduces experimental atherosclerosis." (PMID 35536648, 2022). "Single-cell sequencing revealed that ApoB reactive T cells have different helper T cell phenotypes, thus playing different roles in atherosclerosis." (PMID 36685487, 2022). "Atherosclerosis results from the retention of apolipoprotein B (apo B) containing lipoproteins mostly in the form of low- density lipoproteins (LDL) in the vessel wall." (PMID 36382159, 2022). "In any case though, our studies show that PCSK9 in apoB-depleted plasma does affect the atheroprotective properties of HDL indicating a novel role of PCSK9 in atherosclerosis." (PMID 36067830, 2022). "In recent years, studies on ApoB-related vaccines have shown that the use of ApoB-derived vaccines can clearly inhibit the progression of atherosclerosis." (PMID 35391927, 2022). "Preclinical studies have shown that vaccination against certain ApoB peptides induces an expansion of Tregs and thereby protects from atherosclerosis." (PMID 36684560, 2022). "Atherosclerosis is a chronic inflammatory disease of large arteries that involves an autoimmune response with autoreactive T cells and auto-antibodies recognizing Apolipoprotein B (ApoB), the core protein of low-density lipoprotein (LDL)." (PMID 35479271, 2022). "Antigens related to atherosclerosis, such as native or modified ApoB, can be sensed by circulating, peripheral and arterial-infiltrated DCs, which then migrate toward para-aortic lymph nodes where antigens can be presented to naïve T cells." (PMID 35966516, 2022). "For example, inhibition of liver apoB mRNA in mice reduced apolipoprotein B concentrations and reduced atherosclerosis." (PMID 36470666, 2022). "In hyperlipidemia, diabetes, and atherosclerosis, this is often accompanied by an increase in apolipoprotein B, with changes in apolipoprotein B concentrations in the blood therefore possibly being indicative of health problems caused by lipid metabolism." (PMID 36568987, 2022). "The efficacy of atherosclerosis prevention was assessed for peptides derived from apolipoprotein B100 (ApoB), heat shock protein 60 (HSP60), and complement cascade (peptide A)." (PMID 35269559, 2022). "At the end of the five-year program, the Vaccination in Atherosclerosis group concluded that too many safety issues remained unsolved to allow the start of phase 1 testing of an atherosclerosis vaccine based on apoB peptides." (PMID 35269559, 2022). "In atherosclerosis, ApoB+ T cells increased and gradually transformed into pathogenic TH1/TH17-like cells with pro-inflammatory properties, with only a residual Treg transcriptome." (PMID 36267275, 2022). "As a matter of fact, adjuvant-vaccination approaches are currently being actively developed against oxLDL and apoB-carrying lipoproteins in atherosclerosis." (PMID 33594923, 2021). "Elevated levels of LDL are widely recognized as a cardiovascular risk factor, and abundant data point to chemically modified LDL and ApoB as triggers of most of the features of the pathobiology of atherosclerosis." (PMID 34236046, 2021). "Loss-of-function mutations in the LDL receptor or apoB can result in familial hypercholesterolemia, which is characterized by extremely elevated plasma LDL levels, thus leading to accelerated atherosclerosis." (PMID 34677405, 2021).
atherosclerosis (continued). "Circulating molecules of LDL do not participate directly in atherosclerosis development, but by structural modification of its apoB act as a ligand for macrophages in the arterial wall triggering foam cell formation and initiating atherosclerosis." (PMID 33926446, 2021). "Due to the success of immunization with LDL, vaccination against its main protein component ApoB has gained attention and was shown to be effective in reducing atherosclerosis in several studies." (PMID 33572939, 2021). "Subcutaneous administration of apoB-derived peptides in Apoe−/− mice induces antigen-specific Treg expansion, inhibits effector T cell responses, and decreases atherosclerosis." (PMID 33805071, 2021). "Recent studies identified Apolipoprotein B (ApoB)—the core lipoprotein of LDL, very-LDL, and chylomicron—as an atherosclerosis-associated antigen that is recognized by CD4+ T cells in the context of proinflammatory cytokines and strong co-stimulation." (PMID 33572939, 2021). "It is therefore plausible, but remains experimentally unproven, that early ApoB-reactive Tregs have the ability to prevent atherosclerosis." (PMID 33669769, 2021). "Mice and patients with atherosclerosis harbor increased numbers of proatherogenic ApoB-reactive T-helper cell subsets." (PMID 35097028, 2021). "APOB has been confirmed by many studies to be a gene closely related to lipid metabolism and can play an important role in atherosclerosis, non-alcoholic fatty liver, and cerebrovascular stroke." (PMID 33954113, 2021). "Patients with high ApoB:ApoA1 ratio shared a serum metabolomic profile with adult SLE patients with sub-clinical atherosclerosis; a CD8+ T-cell phenotype with CD8+ T-cells isolated from human atherosclerotic plaque; and had a more active disease trajectory." (PMID 33640328, 2021). "This autoimmune response against ApoB lipoproteins was detected in animal models with atherosclerosis." (PMID 34945738, 2021). "Apolipoprotein B-100 (apoB-100) is a major protein source of autoantigenic peptides in rheumatoid arthritis, atherosclerosis, systemic lupus erythematosus (SLE), and Lyme arthritis." (PMID 33043033, 2020). "Atherosclerosis is a multifactorial disease, triggered mainly by abundant accumulation of apolipoprotein B (ApoB)–containing lipoproteins and chronic vascular inflammation." (PMID 32034521, 2020). "Apolipoprotein B (ApoB) is the major apolipoprotein constituent of low-density lipoprotein (LDL), which is a causal agent for atherosclerosis." (PMID 31988649, 2020). "We also found total ApoB to be a predictor of subclinical atherosclerosis in RA; this observation was to be expected, since all atherogenic lipoproteins carry ApoB100." (PMID 32748862, 2020). "Molecularly, Lp(a) is similar to LDL-c, as it is a particle covalently bound by apoB and apo (a), which carries pathogenic LDL-c and leads to atherosclerosis." (PMID 32703301, 2020). "Apolipoprotein-B (ApoB) is the structural component of atherogenic lipoproteins, lipid-rich particles that drive atherosclerosis by accumulating in the vascular wall." (PMID 31366908, 2019). "Atherosclerosis is initiated by subendothelial retention of apolipoprotein B (apoB)–containing lipoproteins in focal areas of arteries, particularly regions in which laminar flow is disturbed by bends or branch points in the arteries." (PMID 30979062, 2019). "Other studies demonstrated that RSV decreases intracellular concentration of apolipoprotein B (ApoB), cholesterol esters, and triglyceride secretion rate, thus protecting against atherosclerosis." (PMID 30893846, 2019).